IL6 (interleukin 6)
Diseases named in the same sentence as IL6 in open-access papers (continued):
Sharing a sentence is not in itself a finding about the gene and the disease.
psoriasis (continued). "The authors found significantly higher levels of IFN-γ, TNF-α, IL-6, IL-8, IL-12, and IL-18 in patients with psoriasis." (PMID 29619128, 2018). "We further examined the expression of IL-6 from healthy skin and psoriasis lesions in transgenic mice and found a marked reduction of IL-6 by 30% compared with that of control littermates." (PMID 30219085, 2018). "In accordance with these results, immunohistochemistry demonstrated that IL-6 was mainly detected in the basal cell layer of the epidermis, and was expressed in both, let-7bTG and wild-type mice psoriasis lesioned skin." (PMID 30219085, 2018). "Il-6 is also significantly higher in patients with psoriasis and psoriatic arthritis than patients with psoriasis alone." (PMID 29619128, 2018). "The pooled serum levels of TNF-α, IFN-γ, IL-2, IL-6, IL-8, IL-18, IL-22, chemerin, lipocalin-2, resistin, sE-selectin, fibrinogen and C3 were higher in psoriasis patients compared with healthy controls (all P < 0.05)." (PMID 29416693, 2018). "Multiple cytokine signaling pathways that are known to play important roles in psoriasis pathogenesis were enriched in the DEGs, including the IL-1, IL-6 and IL-8 pathways." (PMID 29871627, 2018). "They accepted the treatment of NB-UVB and the following data were collected: serum levels of IL-17 (interleukin), TNF-α (tumor necrosis factor) and IL-6, Psoriasis Area and Severity Index (PASI) scores before and after 10 sections of NB-UVB treatment." (PMID 29390261, 2017). "HaCaT cells were activated with TNF-α and IFN-γ, which are involved in the pathogenesis of psoriasis, and the gene expression of IL-6, which participated in the Th17 cell differentiation and psoriasis, was measured by real-time PCR." (PMID 29138509, 2017). "Among various molecules, the major cytokines that are concurrently expressed in both adipose tissue and skin of patients with psoriasis are IL-6 and TNF-α." (PMID 29232931, 2017). "First, we only selected the serum level of IL-17, TNF-α, IL-6 to represent inflammatory cytokines to clear possible effects of MS on treatment of UVB in patients with psoriasis." (PMID 29390261, 2017). "We also found that oral administration of rottlerin decreased IL-6 and IL-23 mRNA expression in psoriasis-like skin lesions (P<0.01)." (PMID 29272319, 2017). "On the other hand, IL-6 recruits neutrophils and promotes the proliferation of keratinocytes in imiquimod-induced psoriasis-like murine skin." (PMID 29358932, 2017). "Although the etiology of psoriasis has not yet been fully elucidated, the abnormal production of several inflammatory mediators from immune cells such as TNF-α, IL-6, IL-17, IL-22 and IL-23 are confirmed to play a key role in psoriasis." (PMID 29272319, 2017). "Excessive proinflammatory cytokines, such as TNF-α and IL-6, play a key role in the pathogenesis and progress of psoriasis." (PMID 29358932, 2017). "In this study, we deleted the IL-6Rα specifically in the myelomonocytic cells, expecting these mice to develop a milder form of disease–in order to further investigate the role of IL-6 in the context of IMQ-induced psoriasis-like skin disease." (PMID 26999594, 2016). "The involvement of myelomonocytic cells in IMQ-induced psoriasis-like skin disease is undisputed and IL-6 as neutrophil-recruiting cytokine is known to be strongly associated with psoriasis." (PMID 26999594, 2016). "Although the role of regulatory T cells in the pathogenesis of psoriasis remains to be fully elucidated, IL-6 is thought to render effector T cells refractory to regulatory T cell-mediated suppression." (PMID 26573299, 2016). "Mice, that spontaneously develop psoriasis-like disease based on IL-17A overexpression in the skin (K14-IL-17Aind/+), show at least a partial remission of disease after anti-IL-6 treatment." (PMID 26999594, 2016).
psoriasis (continued). "We therefore analyzed the IL-6-mediated signaling in myelomonocytic cells in psoriasis and treated back and ear skin of 7–8 weeks old IL-6RαΔmyel mice and the respective control groups with IMQ or sham cream for 5 consecutive days." (PMID 26999594, 2016). "To further investigate the role of IL-6 signaling in myelomonocytic cells in the context of IMQ-induced psoriasis-like skin disease, we crossed LysM-Cre mice with the IL-6RαFL/FL mouse line." (PMID 26999594, 2016). "IL-6 has also been reported to accelerate proliferation and migration of keratinocytes, leading to skin disorders, including psoriasis." (PMID 27647952, 2016). "As IL-6 is important in the pathogenesis of psoriasis, anti-IL-6 has been discussed as a new treatment option of psoriasis in humans, but stays disputed." (PMID 26999594, 2016). "Although the pathogenesis of psoriasis is not fully understood, evidence suggests that many cytokines, including IL-6, IL-17A, IL17F, IL-22, IL-23 and TNF-α, are involved and interact as a network in the pathogenesis of psoriasis." (PMID 27581210, 2016). "As IL-6-/- mice have been described to develop reduced skin disease after administration of IL-23, IL-23 seems to be the connection between IL-6 and the γδ T cells in psoriasis." (PMID 26999594, 2016). "Previous studies showed that Th17 cell-related cytokines, such as IL-6 and IL-22, are highly expressed in psoriasis, and their pleiotropic effects include epidermal keratinocyte hyperplasia and stimulation of blood vessel formation." (PMID 26893174, 2016). "In the model of IMQ-induced psoriasis-like skin disease, IL-6 is important for recruitment of neutrophils." (PMID 26999594, 2016). "In psoriasis, T-cells (both CD4+ and CD8+) are known to cause low production of Th2 cytokines (IFNγ, TNFα, and IL-2) and high production of Th1 cytokines (IL-4, IL-6 and IL-10), leading to polarization of the type 1 pathway." (PMID 26849645, 2016). "Recently, we demonstrated that IL-17A, IL-22, and IL-6 cytokines were more elevated in serum from psoriasis patients than in heathy controls." (PMID 28042206, 2016). "Many cytokines, including interleukin-23(IL-23), IL-17A, TNF-α, IL-6, IL-1β and IL-22, are also involved in the pathogenesis of psoriasis." (PMID 26007179, 2015). "It is believed that the inflammatory response in psoriasis leads to a Th1 lymphocyte cytokine milieu with increased levels of IL-1, IL-6, IL-8, TNF-α, and markers of systemic inflammation." (PMID 26700640, 2015). "In particular, in the pathophysiology of psoriasis, Th17 cells induce the production of IL-6 and IL-8 in keratinocytes." (PMID 26136626, 2015). "Our findings demonstrate that IL-17A, IL-22, and IL-6 serum concentrations were significantly higher in psoriasis patients than in the control group." (PMID 26351408, 2015). "Elevated levels of IL-6 have been described in patients with PsA compared with patients with psoriasis." (PMID 26339141, 2015). "In this context, we evaluated also the relationship between the CRP levels, produced by the liver under the influence of IL-6 as one of the links between the altered cytokine milieu and psoriasis, and the consumption of EVOO." (PMID 25622660, 2015). "CRP was reduced in patients from all three categories, TNF-α was reduced in patients with CFS and psoriasis, and IL-6 was reduced in those with UC and CFS all as compared to placebo." (PMID 27417751, 2015). "Since serum TNF-α is increased in active psoriasis and correlates with disease severity, higher levels of its downstream cytokines, IL-6 and IL-8, in thick plaque psoriasis likely reflects more biologic activity of TNF-α in thick plaque psoriasis." (PMID 26176783, 2015). "Although our results do not show any correlation between serum levels of IL-17A, IL-22, and IL-6 and disease activity, the present study confirms that they were increased in Brazilian psoriasis patients in comparison to healthy volunteers." (PMID 26351408, 2015).
psoriasis (continued). "Increased activation of STAT3 (pSTAT3) has been detected in lesional skin of psoriatic patients; several cytokines upregulated in psoriasis, including IL-6, IL-20, and IL-22, signal through STAT3 activation." (PMID 25126586, 2014). "On the other hand, elevated levels of IL-6 have been reported in psoriasis either in serum or in lesions." (PMID 25136144, 2014). "Serum levels of IL-6 are regarded as a marker of the inflammatory activity in psoriasis as well as an indicator of treatment response; a positive correlation between IL-6 serum levels and clinical severity of PV before treatment has been described." (PMID 25126586, 2014). "So far, the experience with IL-6 inhibitors in psoriasis is limited, as other signaling pathways have been successfully investigated as therapeutic targets (i.e., TNF-alpha, IL-23, and IL-17)." (PMID 25126586, 2014). "The key pathogenetic role of IL-6 signaling pathway in psoriasis is supported by evidence deriving from mouse models of psoriasis-like skin disease relying on constitutive activation of STAT3 in keratinocytes." (PMID 25126586, 2014). "Furthermore, the percent reduction of the PASI correlated with serum levels of IL-6, but not IL-17 or IL-22, before photo(chemo)therapy, indicating that psoriasis patients with high serum IL-6 levels might be more susceptible to the effects of photo(chemo)therapy." (PMID 23365685, 2013). "Mice with epidermal overexpression of IL-6 (K14-IL-6 transgenic mice) exhibit a psoriasis phenotype." (PMID 23133751, 2012). "Linear regression showed that IL-2, IL-6 and IL-12 levels predicted 66% of corticosterone levels, which were selectively increased in psoriasis mice subject to PSD." (PMID 23226485, 2012). "Psoriasis-like epidermal hyperplasia can be induced in the ears of mice by directly injecting IL-23 and was shown to be IL-6 dependent." (PMID 22229105, 2012). "Psoriasis is a chronic inflammatory skin disorder which is characterized by local and systemic escalation of proinflammatory cytokines such as IL-6 and TNF-α." (PMID 22654590, 2012). "Of these, TNF-α in RA, CD and psoriasis, and IL-6/IL-6R in RA and CD have been shown to be of clinical relevance." (PMID 19884985, 2009). "Chronic systemic inflammation in psoriasis promotes keratinocyte hyperproliferation through the activation of Th1, Th17, and Th22 lymphocytes and increased production of pro-inflammatory cytokines, such as IL-1, IL-6, IL-12, IL-23 and TNF-α." (PMID 41596291, 2026). "In psoriasis, curcumin exhibits its anti-inflammatory effects by reducing the expression of cytokines such as interleukin-17A (IL-17A), interleukin-17F (IL-17F), interleukin-22 (IL-22), IL-6, IL-1β, and TNF-α, and by inhibiting NF-κB activation." (PMID 40718452, 2025). "Consequently, our findings highlight the spleen as a central site for granulopoiesis in the IMQ-induced psoriasis model by IL-6/P-STAT3." (PMID 40890773, 2025). "Psoriasis is a chronic inflammatory condition characterized by systemic inflammation, with elevated levels of proinflammatory cytokines, including interleukin-1β, interleukin-6, and tumor necrosis factor α." (PMID 40861447, 2025). "Emerging evidence highlights the therapeutic potential of targeting IL-6 signaling pathways in psoriasis, and our findings suggest that IL-6–focused interventions may effectively reduce persistent residual inflammation." (PMID 41472738, 2025). "Instead, we observed that the treatment of Mφs with 5 μg/mL CU-LNA-SLNs alone was sufficient to induce a dramatic decrease in IL-6 (70.7% inhibition, as compared to the control, p < 0.05), a cytokine found particularly increased in serum and skin lesions of patients with psoriasis." (PMID 40005020, 2025). "Additionally, IMQ stimulates the release of inflammatory factors such as IL-1β, IL-6, IL-23, and IL-17 leading to produce psoriasis-like symptoms in the skin, including erythema, scaling, and epidermal thickening." (PMID 40072672, 2025).
psoriasis (continued). "IL-6 is upregulated in inflammatory skin conditions such as psoriasis and UVB irradiation." (PMID 41465292, 2025). "In addition, IL-6 release is further enhanced by IL-17 and IFNγ, cytokines involved in the pathogenesis of psoriasis." (PMID 40461723, 2025). "Furthermore, subcutaneous administration of the fused EVs in a psoriasis-like mouse model elevated expression of the M2 macrophage marker Arg1 and significantly reduced levels of inflammatory cytokines, including IL-1β, IL-6, and TNF-α, in affected skin." (PMID 41226338, 2025). "Similarly, our investigation revealed a substantial elevation of IL-6 in the blood, spleen and skin of psoriasis-like mice, accompanied by an accumulation of neutrophils in the spleen and skin of these mice." (PMID 40890773, 2025). "Moreover, daphnetin has been revealed to significantly alleviate erythema, scaling, epidermal thickness, and inflammatory cell infiltration in psoriasis-like mice by attenuating upregulation of IL-6, IL-23A, and IL-17A in the skin lesions of mice." (PMID 41462398, 2025). "Research suggests that low estrogen levels may increase pro-inflammatory cytokine activity, such as TNF-α and IL-6, which are key players in psoriasis pathogenesis." (PMID 39860587, 2025). "Similar to ACD, psoriasis is caused primarily by TNF-α, IL-1β, and IL-6 produced by keratinocytes, which stimulate plasmacytoid dendritic cells to produce interferon-α (IFN-α) followed by its stimulation of IL-12 and IL-23 release by dendritic cells nearby lymph nodes." (PMID 41226679, 2025). "This could be related to the inflammatory activity of adipose tissue, which secretes pro-inflammatory cytokines such as TNF, IL-1, and IL-6, which could further exacerbate systemic inflammation that overlaps with psoriasis." (PMID 39775226, 2025). "While prior studies have documented persistent IL-6 elevation and its cardiovascular implications in psoriasis, our study adds novel insight by highlighting the combined effect of visceral adiposity and residual cytokine activity on IL-6 across different treatment modalities." (PMID 41472738, 2025). "The application of NF-κB antagonists can significantly reduce epidermal thickness, acanthosis, and inflammatory symptoms in psoriasis-like mice.Activation of the NF-κB signaling pathway induces the expression of pro-inflammatory factors such as NO, IL-1β, IL-6, and COX-2." (PMID 40333872, 2025). "We induced HaCaT cells with IL-6 (10 ng/mL) for 24 h to build psoriasis-like cellular model." (PMID 40756706, 2025). "IL-6 is found in the blood serum and skin lesions of patients with psoriasis." (PMID 40906403, 2025). "TNF-α and IL-6 are the important cytokines involved in inflammation in psoriasis." (PMID 40733073, 2025). "Consequently, this study provides further evidence supporting the clinical application mechanism of IL-6 monoclonal antibodies in the treatment of psoriasis." (PMID 40890773, 2025). "While IFNγ and the IL‐17/IL‐23 axis are well established in psoriasis, IL‐4 has been shown to downregulate IL‐1β and IL‐6 production by psoriatic cells and may aid in psoriasis resolution, as observed during treatment with vitamin D3 analogues." (PMID 40926620, 2025). "Furthermore, RT-qPCR analysis of pyroptosis-associated inflammatory cytokines revealed significantly increased expression of IL1β, IL6, and TNFα in psoriasis-derived MDMs compared to healthy controls." (PMID 40722833, 2025). "Therefore, it is of interest to report the correlation between serum levels ofTNF-α, IL-6 and IL-17 with psoriasis severity, providing insights into their utility as immunological markers of diseaseactivity." (PMID 41393395, 2025). "IL-6 is a potential marker of disease activity in patients with psoriasis." (PMID 40906403, 2025). "TGF-β1 has been shown to inhibit keratinocyte growth in psoriasis but may also enhance keratinocyte proliferation as a result of increased levels of inflammatory cytokines and chemokines (IL-1, IL-6, IL-8)." (PMID 40906403, 2025).
psoriasis (continued). "IL-17 and IFN-γ, which play a critical role in the pathogenesis of psoriasis, significantly enhanced the R7-triggered IL-6 secretion, and the Th2 cytokines IL-4 and IL-13, which play a critical role in the pathogenesis of AD, tended to enhance the stimulatory effect of R7 on IL-6 secretion." (PMID 40461723, 2025). "This might be due to the role of pro‐inflammatory cytokines (i.e. TNF‐α, IL‐6, IL‐23 and IL‐17) that can be found in the onset and pathogenesis of both AP and Psoriasis." (PMID 40105908, 2025). "We hypothesize that an increased release of R7 from the differentiated keratinocytes of AD and psoriasis patients fosters the secretion of IL-6 and IL-24, especially from the undifferentiated keratinocytes of the stratum basale." (PMID 40461723, 2025). "This indicates that IL-6 elevation in well-treated psoriasis is primarily cytokine-driven." (PMID 41472738, 2025). "The common pathogenesis of cataract and psoriasis may be related to interleukin-6, C-reactive protein, intracellular adhesion molecule- 1, oxidative stress and so on." (PMID 38585265, 2024). "Dysregulated levels of adipokines, cytokines (such as TNF-α, VEGF, IL-6, IL-8, and IL-12), and inflammatory immune response, driven by Th1, Th19, and dysfunctional adipose tissue; were shown to be responsible for the progression of psoriasis and MetS." (PMID 38683749, 2024). "In addition, the decrease in psoriasis severity after applying Iristatin is mainly explained by the critical inhibition of the IL-6/IL-23/IL-17 axis cytokines, which are the main contributors to the disease pathogenesis." (PMID 38444844, 2024). "Thereafter, C3bot was basally added for 3 days and then to check whether the psoriasis phenotype including the upregulation of IL-6 is altered." (PMID 37707681, 2024). "By downregulating S100A7 expression, this may decrease the production of TNF, IL-6, and IL-8 from neutrophils, which are known to play a crucial role in the pathogenesis of psoriasis." (PMID 38699235, 2024). "In particular, T cells and their cytokines, such as TNF-α, IL-23, IL-12, and IL-6, are known to play a central role in psoriasis pathogenesis, leading to the activation of cascades of inflammatory responses that promote keratinocyte proliferation and neutrophil recruitment." (PMID 38699235, 2024). "Fibroblasts in psoriasis have increased expression of IL-6, CXCL2, CXCL12, and CCL19." (PMID 38642273, 2024). "Dysregulation of IL-6 can lead to skin pathology like fibrosis or psoriasis." (PMID 37707681, 2024). "Furthermore, both necroptosis and ferroptosis in keratinocytes have been implicated in psoriasis and IMQ-induced psoriasis-like dermatitis, through the release of inflammatory cytokines such as S100A8, S100A9, HMGB1, IL-33, IL-1β, and IL-6." (PMID 38429278, 2024). "Last but not least, TBTDC NP-PDT attenuated IMQ-induced up-regulation of inflammatory cytokines, including TGF-β1, IL-1β, IL-17, IL-23, TNF-α, IFN-γ, IL-6, and IL-22, which are important proinflammatory cytokines involved in psoriasis pathogenesis in the skin lesions of mice." (PMID 39109246, 2024). "Thus, IL-6 plays a crucial role in the chronic inflammatory process and promotes atherogenic effects in psoriasis patients." (PMID 39429270, 2024). "In addition, psoriasis and MetS share a common state of chronic low‐grade inflammation, and inflammatory markers such as IL‐6 and TNF‐α are increased in patients with psoriasis and MetS." (PMID 38174774, 2024). "Increased IL-6 production in patients affected by psoriasis has been extensively described and correlated to several pathological effects within affected tissues, including differentiation of type-17 lymphocytes and dampening of regulatory T (Treg) cell function." (PMID 38495872, 2024). "Studies have shown that IL-6 plays an active role in initiating T helper 17 cell development, which may aggravate psoriasis inflammation." (PMID 39720727, 2024).